NOTCH1 (notch receptor 1)
Diseases named in the same sentence as NOTCH1 in open-access papers (continued):
Sharing a sentence is not in itself a finding about the gene and the disease.
cardiac hypertrophy (10 papers, 2013 to 2025). "Developmental SHP2 dysfunction underlies cardiac hypertrophy in Noonan syndrome partially through the decreased NOTCH1/EPHB2 signaling." (PMID 39329089, 2024). "Our results will help to understand the underlying mechanism of Notch1 on physiological cardiac hypertrophy." (PMID 36834623, 2023). "Combined with the morphological staining data, our results suggest that the deficiency of Notch1 led to a lower degree of cardiac hypertrophy after voluntary running." (PMID 36834623, 2023). "In summary, we found that Notch1 may be involved in the cardiac hypertrophy process of mice caused by voluntary running." (PMID 36834623, 2023). "We infer that a deficiency of Notch1 may affect the activation of p38 after voluntary running, then it could reduce the β-catenin expression, and finally decrease the degree of cardiac hypertrophy." (PMID 36834623, 2023). "Deficiency of Notch1 could reduce the degree of cardiac hypertrophy." (PMID 36834623, 2023). "In this experiment, we evaluated the effect of Notch1 in voluntary wheel-running-induced cardiac hypertrophy of mice and explored the relevant molecular mechanism of Notch1 in this process." (PMID 36834623, 2023). "The degree of cardiac hypertrophy in the Notch1+/− RUN mice was lower than that of their littermate control." (PMID 36834623, 2023). "We posit that our study will provide a potential therapy for cardiac hypertrophy, especially for patients, whose heart disease is related to the Notch1 gene." (PMID 36834623, 2023). "Notch1 plays an important role in cardiac hypertrophy; however, the experimental results are inconsistent." (PMID 36834623, 2023). "In conclusion, Notch1 plays a critical role in physiologic cardiac hypertrophy through the p38 signaling pathway." (PMID 36834623, 2023). "The results found that inhibition of Notch1 significantly promoted postpartum ventricular dilatation, myocardial hypertrophy and myocardial interstitial fibrosis and suppressed myocardial angiogenesis." (PMID 32529705, 2020). "In this experiment, we aimed to explore the role of Notch1 in physiological cardiac hypertrophy." (PMID 36834623, 2023). "This implies that Notch1 may play an important role in the degree of cardiac hypertrophy after voluntary running." (PMID 36834623, 2023). "However, inhibition of Notch1 by LY‐411575 markedly exacerbated LV dilatation, myocardial hypertrophy, interstitial fibrosis and LV dysfunction." (PMID 32529705, 2020). "In the Notch1 activated heart, pressure overload-induced Akt phosphorylation was reduced, which could explain the decrease in cardiac hypertrophy." (PMID 27510556, 2016). "At the same time, the cardiac autophagy of the Notch1+/− CON group was also increased, accompanied by cardiac hypertrophy and a decrease in cardiac function." (PMID 36834623, 2023). "Notably, the pro-ventricular hypertrophy effect of Notch2 is quite different from the functions of Notch1 and Notch3 in cardiac development, since mice lacking each of them develop HCM." (PMID 40104444, 2025). "Considering the running duration of mice, we were not sure whether or not there would be a difference in the degree of cardiac hypertrophy between the Notch1+/− CON and Notch1+/− RUN groups after running longer." (PMID 36834623, 2023). "In the present study, we therefore examined the possibility that inhibition of NOTCH1 or NOTCH2 signaling in vivo in a situation of cardiac hypertrophy may facilitate the emergence of CMs from non-myocyte origins." (PMID 35448087, 2022). "NOTCH1, but not NOTCH2 blockade, blunted the development of cardiac hypertrophy and fibrosis, and preserved cardiac function in mice subjected to pressure overload." (PMID 35448087, 2022).
malignant glioma (10 papers, 2012 to 2024). A grade III or grade IV glioma arising from the central nervous system. "Specifically in the context of malignant glioma, these include NOTCH1, NOTCH2, MET, and CDK6." (PMID 22479456, 2012).
osteoarthritis (10 papers, 2009 to 2024). A noninflammatory degenerative joint disease occurring chiefly in older persons, characterized by degeneration of the articular cartilage, hypertrophy of bone at the margins and changes in the synovial membrane. "Previous studies showing suppression of NOTCH1 potentially attenuated osteoarthritis provide additional support to this notion." (PMID 32674293, 2020). "The aim of this study was to examine the distribution of stem cell markers (Notch-1, Stro-1 and VCAM-1) and of molecules that modulate progenitor differentiation (Notch-1 and Sox9) in normal adult human articular cartilage and in osteoarthritis (OA) cartilage." (PMID 19500336, 2009). "ADAMTS5, NOTCH1, SMAD9, and SOX9 genes, enriched in the osteoarthritis pathway, were predicted as targets of a novel miRNA (3_17250)." (PMID 32316683, 2020). "NOTCH1 is the most abundantly expressed NOTCH receptors in normal cartilage and its expression increases in osteoarthritis (OA), when chondrocytes exit from their healthy “maturation arrested state” and resume their natural route of proliferation, hypertrophy, and terminal differentiation." (PMID 34769441, 2021). "However, cells in mechanically damaged cartilage migrate to the injured site, and cells in early-stage osteoarthritis (OA) express surface markers such as CD105 and CD166 and exhibit stem-cell-related markers such as Notch-1, STRO-1, and vascular cell adhesion molecule-1 (VCAM-1)." (PMID 35296296, 2022).
ovarian tumor (10 papers, 2005 to 2025). "There was a significant correlation (0.01 level, two-tailed) between the grading and staging of ovarian tumours and Notch1 expression." (PMID 37489207, 2023). "Various studies have detected Notch1 and Notch3 expression in ovarian tumors by IHC, real-time polymerase chain reaction, and/or immunoblotting." (PMID 25072022, 2014). "Consistent with published work, we similarly detected cleaved Notch1 in OvCa cell lines and primary ovarian tumor samples by immunoblotting." (PMID 25072022, 2014). "To study the Notch 1 mRNA expression level we used TaqMan real-time quantitative RT–PCR for the screening of human ovarian tumours and cell lines." (PMID 16136053, 2005). "These lncRNAs were identified with in silico analyses using The Cancer Genome Atlas and the results were validated using our transcriptome data from the in vitro NOTCH1/3 silencing experiments and the qRT-PCR analysis, using tissue samples from patients with ovarian tumors." (PMID 35326706, 2022). "We show that endothelial FABP4 expression requires NOTCH1 and VEGFA signalling, and is required for ovarian tumour angiogenesis." (PMID 27568980, 2017).
pancreatic ductal adenocarcinoma (10 papers, 2012 to 2025). An infiltrating adenocarcinoma that arises from the epithelial cells of the pancreas. "The interaction between PrPC and Notch1 also stimulated the growth and invasion of pancreatic ductal adenocarcinoma." (PMID 38370370, 2024). "Notch1 expression could be detectable in pancreatic ductal adenocarcinoma cases, and Notch1/Hes1 signaling is reactivated; however, Notch1 as a feto-oncoprotein is activated during organogenesis and carcinogenesis." (PMID 35154607, 2021). "In addition, nuclear Notch-1 was reported to be degraded after targeting XPO1 in pancreatic ductal adenocarcinoma." (PMID 32661323, 2020).
Sepsis (10 papers, 2015 to 2025). Sepsis is defined as life-threatening organ dysfunction caused by a dysregulated host response to infection. "More interestingly, Notch1 was reported to be implicated in the pathogenesis of sepsis." (PMID 33817242, 2020). "Given the close relationship between Notch1 signaling and mitochondria, we detected the impact of BBR on Notch1 signaling in rats with CLP-induced sepsis." (PMID 39568588, 2024). "Collectively, these results demonstrated that BBR potentially alleviated mitochondrial dysfunction via up-regulating Notch1 signaling in sepsis rats." (PMID 39568588, 2024). "In summary, our study suggests that NICD in the Notch1 signaling pathway is a promising target for the treatment of sepsis." (PMID 37205094, 2023). "Here, we report a previously uncharacterized role of Notch1 in mediating vascular permeability during sepsis." (PMID 37205094, 2023). "To investigate the role of the Notch1 signaling pathway in sepsis-induced vascular injury, we used a Notch1 receptor-targeted drug, TGN, to inactivate the Notch1 signaling pathway." (PMID 37205094, 2023). "Further, we evaluated the level of NICD (activated or cleaved Notch1) to assess the functional consequence of sepsis-induced change in mRNA expression of Notch1 receptor at the level of downstream pathway activity." (PMID 35190630, 2022). "Although significantly upregulated in LPS-induced sepsis, miR-146b seems to suppress the inflammatory processes involved, as portrayed by a reduction of IL-1β and cellular apoptosis, probably by targeting Notch1." (PMID 31671621, 2019). "In lipopolysaccharide (LPS)-induced sepsis, the levels of Notch signaling molecules, including Notch1, Notch2, Hes1, and intracellular domain of Notch (NICD), were increased." (PMID 29867921, 2018). "Then, we confirmed that CLP sepsis activated Notch-1 signaling in HSPCs, demonstrating that this pathway was responsible for the sepsis-induced proliferation and expansion of HSCs." (PMID 26272069, 2015). "Thus, the Notch1 signaling pathway is a potential target for the treatment of sepsis." (PMID 37205094, 2023). "However, the effect of the intracellular domain of Notch1 (NICD) on EC injury in sepsis remains unclear." (PMID 37205094, 2023). "Thus it may not be unreasonable to infer that the changes observed in the Notch targets following sepsis were attributed to the change in the activity of both Notch1 and Notch3 signalling." (PMID 35190630, 2022). "We found a previously uncharacterized role of Notch1 in mediating vascular permeability during sepsis, and we showed that inhibition of NICD resulted in vascular EC dysfunction in sepsis, which was reversed by melatonin." (PMID 37205094, 2023). "miR-150-5p alleviated LPS-induced inflammatory response and apoptosis at least partly by targeting Notch1 in RAW264.7 cells, highlighting miR-150-5p as a target in the development of anti-inflammation and anti-apoptosis drugs for sepsis treatment." (PMID 33817242, 2020). "Other studies showed that Cav1 coordinated and coupled with Notch1/HES1 in the liver tissue of LPS–induced septic mice, which promoted the production of IL–10 in macrophages, leading to inhibition of inflammation in a model of sepsis." (PMID 35911737, 2022). "Sepsis did not produce significant change in Notch1 mRNA transcript expression in mouse aorta, albeit, there was 32.71% decrease in the mRNA expression as compared to SO mice (0.72 ± 0.10 vs. 1.07 ± 0.16, n = 7–8)." (PMID 35190630, 2022). "In conclusion, we first identified that miR-150-5p exerted anti-inflammation and anti-apoptosis function at least partly by targeting Notch1 in LPS-induced RAW264.7 macrophages, highlighting miR-150-5p as a target in the development of anti-inflammation and anti-apoptosis drugs for sepsis treatment." (PMID 33817242, 2020). "However, the significance of Notch1 signaling, especially NICD, in sepsis-induced vascular dysfunction is unknown." (PMID 37205094, 2023).
aortic stenosis (9 papers, 2017 to 2024). Aortic valve stenosis is a aortic valve disease caused by the incomplete opening of the aortic valve. "Subsequently, other groups have reported cases of patients with variants in NOTCH1 who presented aortic coarctation or aortic stenosis and TAV." (PMID 37239988, 2023). "In this connection, a study investigating the role of NOTCH1 mutations in Aortic Stenosis (AS), found a highly significant association of rs2229974 with AS, which will likely have an impact on an individual’s exercise performance ability." (PMID 37471354, 2023). "In the case of the induction of severe calcification that may lead to aortic stenosis, utilizing a more suitable mouse model for valvular calcification such as Notch1+/− mice would be more appropriate." (PMID 36115863, 2022).
aortic valve stenosis (9 papers, 2017 to 2025). Aortic valve stenosis (AVS) is a condition characterized by narrowing of the heart's aortic valve opening. "Mutations in the NOTCH1 gene are known to cause aortic valve stenosis and calcific atrioventricular disease, which are important factors in the development of heart disease." (PMID 40303613, 2025). "We have generated and studied a conditional Notch1 knockout mice model in which Notch1 was specifically deleted in VECs, and the mutant mice display the typical phenotypes of aortic valve stenosis at a young age of 3 months." (PMID 34239905, 2021). "We have found by echocardiography that the adult VEC Notch1 conditional knockout mice display increased peak velocity across the aortic valve, indicating a phenotype of aortic valve stenosis." (PMID 34239905, 2021). "Here, we report the whole‐exome sequencing in members of a nuclear pedigree affected by BAV, ventricular septal defect (VSD), aortic valve stenosis, and TAA segregating with a pathogenic NOTCH1 mutation." (PMID 32720365, 2020). "Moreover, in the interstitial cells of human aortic valve stenosis, Notch1 enhances the inflammatory response and promotes the osteogenic response under the stimulation of TLR4 by regulating the activation of NF-κB." (PMID 35891967, 2022). "Accumulating evidence links NOTCH1 signaling with the development of aortic valve stenosis." (PMID 32720365, 2020).
clear cell renal cell carcinoma (9 papers, 2012 to 2025). "To investigate how NOTCH1 signaling pathway participates in the development of clear cell renal cell carcinoma (ccRCC), at first, we sought to identify the mutated gene(s) related to NOTCH1 signaling pathway based on TCGA KIRC cohort." (PMID 36973704, 2023). "Notch1, the most studied member of the family, was shown to induce tubular hyperplasia when overexpressed in tubular epithelial cells, and Notch1 and Jagged1 are overexpressed in human clear cell renal cell carcinoma (ccRCC) compared to normal kidneys." (PMID 35055068, 2022). "In a cohort of 52 clear cell renal cell carcinoma patients, knockdown of NOTCH1 was shown to induce apoptosis, suggesting that targeted inhibition of NOTCH1 may represent a promising therapeutic approach for eliminating malignant cells." (PMID 41465847, 2025). "Moreover, the overexpression of Notch1 intracellular segment in VHL knockout mice revealed accumulation of intracellular fat, cytoplasmic dysplasia nests, and upregulated expression of Hey1 and Hey2 downstream of the Notch pathway, similar to human renal clear cell carcinoma." (PMID 35096263, 2022).
heart failure (9 papers, 2014 to 2025). Inability of the heart to pump blood at an adequate rate to meet tissue metabolic requirements. "The prognostic associations of NOTCH1 and Spondin-1 were attenuated after adjustment for history of heart failure, but remained significant at p<0.01." (PMID 30557359, 2018). "Hypertension and heart failure correlated with all proteins, except NOTCH1 and CDKN1A, respectively." (PMID 41054850, 2025). "Activation of SIRT1 plays a crucial role in mitigating EndMT by modulating the neurogenic locus notch homolog protein 1 (Notch1) and TGF-β/Smad2/3 pathways, thereby reducing fibrotic responses associated with heart failure." (PMID 41011644, 2025). "Although literature has shown that the Notch signaling system exists in myocardial cells and is activated during heart failure, and Notch3 and Notch4 may be the main receptors involved, more studies have reported a close relationship between Notch1 and cardiovascular disease." (PMID 38841263, 2024).
Hypertension (9 papers, 2015 to 2025). The presence of chronic increased pressure in the systemic arterial system. "Logistic regression indicated associations between AMI and reduced Notch1 expression, hypertension, smoking, and high fasting glucose." (PMID 38841263, 2024). "Logistic regression analysis showed that low levels of Notch1 protein, hypertension, smoking, and high fasting blood glucose were all associated with AMI." (PMID 38841263, 2024). "Logistic regression analysis indicated that AMI was linked with reduced levels of Notch1, as well with hypertension, smoking, and high levels of fasting glucose." (PMID 38841263, 2024). "miR-31-5p is involved in the function of vascular endothelial cells via targeting ETBR, Notch 1, or eNOS, but little is known about the roles and targets of miR-31-5p in the VSMCs of hypertension." (PMID 34440213, 2021). "In an age- and arterial hypertension-adjusted multivariable regression analysis, the serum OPG levels and the OPG/sRANKL ratio were correlated with NOTCH1 missense variants." (PMID 28246602, 2017). "Additional studies examining the aorta after pharmacologic treatment to induce hypertension (angiotensin II or phenylephrine infusion) of Notch1+/− and Notch1+/−; Nos3−/− may give a more definitive picture of the role on Notch1 in this disease." (PMID 25914885, 2015).